TRPV1 (transient receptor potential cation channel subfamily V member 1)
Diseases named in the same sentence as TRPV1 in open-access papers (continued):
Sharing a sentence is not in itself a finding about the gene and the disease.
migraine (continued). "Furthermore, ethanol, a well-known trigger of migraine, has been reported to induce TRPV1 activation." (PMID 28649203, 2017). "Associated release of neuropeptide CGRP from TRPV1/TRPA1 positive peptidergic nerve fibers should further support both neuronal sensitization and the long-lasting nociceptive firing underlying migraine pain." (PMID 28798669, 2017). "TRPV1, TRPM8 and TRPA1 have all been linked to migraine pathophysiology." (PMID 27854251, 2016). "Expression of TRPV1 and modulation of its function, trafficking and expression by multiple mediators in trigeminal neurons have been proposed to be involved in the development of migraine pathophysiology." (PMID 27854251, 2016). "Thus, the role of the TRPV1 in migraine pain is still controversial to date, and the downstream regulatory mechanisms underlying the actions of artemin and GFRα3 on migraine pain require to be studied further." (PMID 27600145, 2016). "Furthermore, TRPV1 channels in the TNC or in dissociated trigeminal neurons were shown to be inhibited by the common migraine drug sumatriptan." (PMID 26109436, 2015). "Our results describe two TRPV1 antagonists that are effective in two in vivo models of migraine." (PMID 26109436, 2015). "Based on our findings, we conclude that TRPV1 may play a role in the pathophysiological mechanisms, which are relevant to migraine." (PMID 26109436, 2015). "A growing number of TRP channels are of potential therapeutic interest to treat pain conditions Clinical trials with potent, small molecule antagonists targeting thermoTRPs, mainly TRPV1 are on-going for diverse indications encompassing chronic pain, neuropathic pain, and migraine." (PMID 24288041, 2011). "Usefulness of the TRPV1 blockade has been demonstrated to be beneficial in pain induced by Herpes zoster, diabetic peripheral neuropathy, bone cancer, arthritis, inflammatory bowel disease and migraine." (PMID 19753113, 2009). "It is noteworthy that the TRPV1 gene encodes transient receptor potential vanilloid type 1 ion channels, which are expressed in trigeminal nociceptors and whose activation leads to the release of calcitonin gene-related peptide (CGRP), which is now recognized as a primary mediator of migraine pain." (PMID 39105976, 2025). "TRPV1 rs222741 and TRPM8 rs7577262 may associate with migraine comorbidity anxiety risk." (PMID 37303955, 2023). "Therefore, this experiment established migraine model rats with inflammation soup to explore whether the XMT extract works by regulating the TRPV1-CGRP/CGRP-R pathway." (PMID 35350752, 2022). "However, in contrast to the protective vasodilatory action of TRPV1 against ischemia reperfusion injury in the heart, CGRP release associated with neurogenic dural vasodilation is thought to be important in the generation of migraine pain." (PMID 33613196, 2020). "Thus, the persistent activation of nociceptors in capsaicin-sensitive nerve fibers shown here may be involved in trigeminal pain signaling and plasticity along with the release of migraine-related neuropeptides from TRPV1 positive neurons." (PMID 26283923, 2015). "Stimulation of these trigeminal afferents through activation of TRPV1 causes a CGRP-mediated increase in dural blood flow and activation of second order neurons in the TNC, and these mechanisms could be involved in the initiation of migraine attacks." (PMID 26109436, 2015). "Therefore, antagonists of TNF-a and TRPV1 may be effective in stress-related migraine." (PMID 38802819, 2024). "TRPV1 and TRPA1 channels are expressed by peptidergic trigeminal neurons, which synthesize and store the main migraine mediator CGRP." (PMID 37123270, 2023). "Among the TRP channels, TRPV1, TRPA1, and TRPM8 have been well studied and are being investigated as potential therapeutic targets for migraine prevention and treatment." (PMID 37175602, 2023).
migraine (continued). "The interest in the involvement of TRP channels in migraine pathophysiology is mainly due to their expression on meningeal nociceptors, in particular TRPA1, TRPM8, TRPV1, and TRPV4, and their role in CGRP release from sensory nerve endings upon activation." (PMID 36986537, 2023). "TRPV1 and TRPV4 are abundantly expressed in primary sensory neurons and play a primary role in migraine pain." (PMID 37303955, 2023). "Capsaicin and ethanol are known to release the pro-migraine neuropeptide, CGRP, from terminals of TRPV1+ve and TRPA1+ve DRG neurons." (PMID 37101198, 2023). "It is concluded that by inhibiting the release of CGRP in the TRPV1-CGRP/CGRP-R signaling pathway in the trigeminal neurovascular system of migraine, it can provide a new strategy for migraine treatment." (PMID 35350752, 2022). "In this study, the positive expression, mRNA expression, and protein expression of TRPV1, CGRP, CRLR, and RAMP1 in the trigeminal nerve of migraine model rats significantly increased." (PMID 35350752, 2022). "A recent study points to a functional cross-talk between TRPV1 and TRPM8 in trigeminal ganglion neurons as a possible mechanism for explaining how facial TRPM8 activation can suppress TRPV1 activity, relieving migraine pain." (PMID 34445208, 2021). "The results of this study indicate that CGRP, COX-2, TRPV1, and TRPA1 immunoreactive cells increased in the TG in the NTG-induced migraine rat model, and these increases were reduced by auricular ES pretreatment." (PMID 31885641, 2019). "However, transient receptor potential (TRP) channels have been repeatedly linked to the disorder, including TRPV1, TRPV4, TRPM8, and TRPA1, based on their activation by pathological stimuli related to attacks, or their modulation by drugs/natural products known to be efficacious for migraine." (PMID 30970581, 2019). "One of the first TRP channels to be investigated was TRPV1, which is activated by capsaicin and also sensitive to endocannabinoids, endovanilloids, lipoxygenase metabolites, nerve-growth factor, and prostaglandins, among other factors many of which may be relevant for migraine." (PMID 30970581, 2019). "Recent studies have demonstrated a potential role of transient receptor potential vanilloid type-1 receptor (TRPV1) and transient receptor potential ankyrin 1 (TRPA1) channels in the pathophysiology of migraine pain." (PMID 26184313, 2015). "Taken together, these findings emphasize the importance of the interplay of TRPV1 and CGRP in migraine-related processes." (PMID 26109436, 2015). "Furthermore, it is noteworthy that capsaicin and other TRPV1 agonists have shown some efficacy in migraine and cluster headache after peripheral administration (for review, see Oxford and Hurley, 2013), using methods which are likely to inhibit only a small subpopulation of TRPV1 expressing neurons." (PMID 25077949, 2014). "Although there is no specific information on the role of these channels to peripheral nociceptor sensitization or central sensitization in migraine, it is possible that TRP channels, and in particular TRPV1 and TRPA1, contribute to this key mechanism." (PMID 23941062, 2013). "Recent studies have highlighted a potential role for new genes, like MTHFR, KCNK18, TRPV1, TRPV3, and new neurotransmission systems, like the hypocretin system, both in migraine and cluster headache." (PMID 23848401, 2013). "Several neuropeptides contribute to the development of migraine pain: for example, CGRP increases the expression and the membrane targeting of P2X3 receptors, and bradykinin upregulates TRPV1 channels." (PMID 24312267, 2013). "The traditional Chinese medicine formula, Xiongshao Zhitong granules (XSZT), alleviates nitroglycerin‐induced migraine‐like behaviors by downregulating CGRP, TNF‐α, IL‐1β, and IL‐18 levels and reducing mast‐cell degranulation via suppression of the TRPV1/Ca2+/NLRP3 signaling pathway." (PMID 41399206, 2025).
migraine (continued). "The transient receptor potential (TRP) channels, particularly TRPV1 (activated above 43 °C) and TRPV4 (responding to 24–35 °C), play a key role in migraine development by triggering inflammation and releasing pro-inflammatory agents like calcitonin gene-related peptide (CGRP) and substance p." (PMID 41302667, 2025). "TRPV1 activation in TG neurons triggers the release of CGRP that induces vasodilation and neurogenic inflammation within the meninges in experimental animals, mimicking migraine." (PMID 39253381, 2024). "TRPV1 and TRPA1 potentially play a role with CGRP in headaches and are also involved in sensitivity to environmental factors such as heat, pH changes, and natural migraine triggers." (PMID 36831105, 2023). "Lastly, nociceptive receptors such as transient receptor potential cation channel subfamily V member 1 (TrpV1) are also receiving attention as they may play a role in various functional pain disorders, including IBS and migraine." (PMID 37291550, 2023). "Considering the importance of intracranial sensitization in the pathomechanism of migraine, the functional sensitization of TRPA1, TRPV1, and other TRP receptors involved in intracranial pain sensation at the receptor level should be discussed as a provocative factor in migraine attacks." (PMID 36982450, 2023). "Differently, the associations of TRPV1 rs8065080 and GRIK2 rs2227283 with migraine were not significant due to the small sample size in matched data." (PMID 37303955, 2023). "In view of the variable success of migraine treatment with BoNT/A (see Section 1), the ability of this protease to block the CGRP release evoked by activating TRPV1 to different extents with a range of capsaicin concentrations was examined using rat TGNs in culture." (PMID 35202143, 2022). "TRPV1 is also sensitive to endocannabinoids, endovanilloids, nerve-growth factor (NGF), and prostaglandins (PGs), which may be relevant for migraine." (PMID 36614146, 2022). "Given the knowledge we have gained regarding TRPV1 and pain, and also that regarding TRPV1 and CGRP levels in migraine, it is conceivable that cannabinoids could play a role in migraines." (PMID 36077412, 2022). "Sumatriptan is a migraine abortive substance through vasoconstriction and inhibition of CGRP secretion from trigeminal ganglion and may also act as TRPV1 desensitizer." (PMID 35002925, 2021). "A number of these channels, including transient receptor potential cation channel subfamily A, member 1 (TRPA1); subfamily V, member 1 (TRPV1), subfamily V, member 4 (TRPV4), and subfamily M, member 8 (TRPM8) are highly expressed in primary sensory neurons and play a role in migraine." (PMID 34790097, 2021). "Therefore, we suggest that auricular ES pretreatment is beneficial for the treatment of migraine and this effect is partly related to CGRP/COX-2/TRPV1/TRPA1 signaling pathways." (PMID 31885641, 2019). "The TRPV1 and TRPA1 channels play a critical role in migraine pathophysiology." (PMID 31885641, 2019). "This does not exclude a possibility for TRPV1 in migraine pathology, but it casts serious doubt on selective TRPV1 antagonism as a therapeutic approach and suggests that activation of TRPV1 alone is not sufficient to generate the headache phase of migraine." (PMID 30970581, 2019). "Although this outcome does not exclude a contribution of TRPV1 to migraine pathology, it indicates that selectively targeting TRPV1 alone is not sufficient for acute treatment of migraine attacks." (PMID 31336748, 2019). "Besides capsaicin, other TRP channel agonists have been described as migraine triggers, thereby placing TRPV1, TRPA1, and TRPM8 in the therapeutic spotlight for the development of migraine treatments." (PMID 30155469, 2018). "Activation of TRPV1 and TRPA1 on meningeal nerve endings induces the release of vasoactive neuropeptides CGRP and substance P and contributes to different forms of headache including migraine." (PMID 28798669, 2017).
migraine (continued). "Activation of TRP channels, such as TRPV1 and TRPA1, has been reported to induce the trigeminal calcitonin gene-related peptide pathway, which mediate neurogenic inflammation, thus leading to the migraine attacks." (PMID 28649203, 2017). "Our data indicate that more than half of the active clusters of meningeal spikes respond to the classical algogen capsaicin indicating a high functional pool of TRPV1 positive fibers in the meningeal nervus spinosus innervating region of MMA, a receptive field for migraine pain." (PMID 26283923, 2015). "In addition to concerted contribution to CGRP release, TRPV1 and TRPA1 receptors making common functional units in the same population of trigeminal neurons can also together contribute to migraine pain." (PMID 26283923, 2015). "However, the TRPV1 antagonist SB-705,498 showed no benefit in a clinical migraine study, highlighting that therapies targeting this receptor alone are insufficient for effectively treating migraine symptoms." (PMID 39407099, 2024). "Notably, we found that resolvin D3 significantly inhibited TRPV1 activity and CGRP release in both mouse and human DRG neurons and may represent a new anti-migraine drug." (PMID 37175602, 2023). "Even already available evidence implicates TRPV1 in pathological pain (inflammatory, visceral, cancer, neuropathic), various respiratory conditions (including chronic cough, asthma), IBD, cardiovascular diseases, interstitial cystitis, urinary incontinence, pancreatitis, and migraine." (PMID 33613196, 2020). "Such sensitization can partly be attributed to TRPV1 and may also explain why migraine patients do not tolerate ambient temperature changes." (PMID 31336748, 2019). "Indeed, in a recent study, two TRPV1 antagonists, JNJ-38893777 and JNJ-17203212, reduced or even completely abolished capsaicin-induced CGRP release from TG neurons in two different animal models of migraine." (PMID 31336748, 2019). "In conclusion, the therapeutic effectiveness of BoNT-A in migraine prevention may be explained by the simultaneous lowering of CGRP release, sensitivity to molecules that activate nociceptive meningeal C-afferents via TRPV1 and TRPA1, and pre-existing inflammation." (PMID 36668895, 2023). "Therefore it does not appear that TRPV1 antagonism in itself is a sufficient migraine target, but the data presented here show that it could potentially be combined with other drugs targeting the eCB system." (PMID 35189809, 2022). "Moreover, we explore non-canonical ECS pathways, including TRPV1, D2 dopamine receptors, serotonergic and ion channel interactions, and their roles in modulating CGRP release and trigeminovascular signaling to treat migraine pathophysiology." (PMID 41549028, 2026).
diabetes (77 papers, 2005 to 2026). "The diabetes-associated lipid mediator 12(S)-HETE activates intracellular TRPV1 in endothelial cells, leading to calcium influx, reactive oxygen species (ROS) generation, and endothelial nitric oxide synthase (eNOS) uncoupling." (PMID 41463571, 2025). "TRPV1 is linked to diabetes mellitus on multiple fronts, encompassing pancreatic function and insulin secretion, appetite regulation, and energy expenditure or thermogenesis." (PMID 39315294, 2024). "Consistent with known pathogenesis of diabetes and diabetic complications, acute hyperglycemia-induced loss of TRPV1+ intraepidermal nerve fibers and disrupted development of epidermal layer by ROS accumulation rather than apoptosis." (PMID 36932093, 2023). "This proves that depletion of TRPV1 expressing neurons prevents diabetes, which is genetically predisposed to type 1 diabetes in mice." (PMID 36234927, 2022). "TRPV1 is involved in the pathophysiology of conditions including chronic inflammatory pain, asthma, cystitis, diabetes-associated peripheral neuropathy, and hearing loss." (PMID 35115924, 2021). "Activation of both P2X3 and TRPV1 has been linked to chronic inflammatory pain conditions and peripheral neuropathy, as observed in diabetes-induced neuropathy." (PMID 32104520, 2020). "Subsequently, Sun and collaborators analyzed TRPV1 involvement in oxidative-stress-induced endothelial dysfunction in diabetes, which represents one of the major cardiovascular risk factors." (PMID 32471282, 2020). "TRPV1 contributes to primary sensory neuronal sensitisation in many pain states, including diabetes, and the degree of behavioural hypersensitivity is associated with increased agonist-evoked TRPV1 activity." (PMID 29930087, 2018). "Activation of TRPV1 has been linked to chronic inflammatory pain conditions and peripheral neuropathy, as observed in diabetes." (PMID 24861977, 2014). "Ablation of these TRPV1 positive sensory afferents by capsaicin application prevents the onset of diabetes and associated pancreatitis in diabetes prone non obese diabetic mice." (PMID 19305794, 2008). "We propose that insulin and IGF-I therapy, partially working through TRPV1, can improve complications associated with diabetes mellitus." (PMID 15857517, 2005). "Moreover, prolonged H2O2 exposure disrupts TRPV1-dependent coronary vascular signaling, which can cause in-tissue perfusion impairments observed in diabetes." (PMID 33716794, 2021). "As 4-HNE and H2O2 impair TRPV1 function, they may further lead to a deficiency in nitric oxide production, a central characteristic of diabetes-induced endothelial dysfunction in this review, when illustrating 12(S)-HETE) and TRPV1 interaction." (PMID 34680034, 2021). "The use of clinically available TRPV1 antagonists may provide a new means to combat bone problems associated with diabetes." (PMID 27468810, 2016). "Multiple studies utilizing TRPV1 antagonists in rodents and induction of neuropathy in Trpv1−/− mice have demonstrated a significant role for TRPV1 in neuropathic pain, mainly associated with diabetes and chemotherapeutic drug use." (PMID 27854251, 2016). "Therefore, capsaicin-induced depletion of TRPV1-expressing neurons prevents the development of diabetes in mice that are genetically predisposed to type 1 diabetes." (PMID 27367653, 2016). "Associations between single nucleotide polymorphisms (SNPs) in the Trpv1 gene and diabetes risk have been reported, indicating that genetic variation may influence channel function, immune reactivity, or vascular tone, thereby modulating individual susceptibility to T1D." (PMID 41463571, 2025). "Thus, it has been proposed that dietary agonists of endothelial TRPV1 could be employed to rescue coronary vasodilation in the presence of multiple cardiovascular risk factors, including diabetes, atherosclerosis, and metabolic syndrome." (PMID 32471282, 2020).